KRAS (KRas proto-oncogene, GTPase)
Diseases named in the same sentence as KRAS in open-access papers (continued):
Sharing a sentence is not in itself a finding about the gene and the disease.
tumor (continued). "High plasma circulating tumor DNA levels were observed for patients carrying a KRAS A146 mutation versus those with a KRAS G12 mutation, with median mutant allele frequencies of 48% versus 19%, respectively." (PMID 34820593, 2021). "Of note, the KRAS variants identified in cfDNA by TST170 showed high concordance with tumor tissue and cfDNA analyzed by BEAMing." (PMID 34640513, 2021). "Conversely, a subset of NSCLCs defined by KRAS/STK11 co-mutation has been found to be associated with a “cold” tumor immune microenvironment and marked resistance to anti-PD-1/PD-L1 therapy." (PMID 34625620, 2021). "Treating clinicians should timely ensure the availability of a complete panel of currently targetable genetic tumor alterations needed for second-line treatment decisions, such as the presence of a KRAS p.G12C mutation." (PMID 34885206, 2021). "A similar result was observed in KRAS-driven cancer cell lines where the antiproliferative effects of CQ were similar between ATG7-deficient tumor cell lines with undetectable autophagic flux and ATG7-efficient tumor cell lines." (PMID 33718194, 2021). "It achieved a significant reduction of both WT and mutant KRAS, impairing cell growth of KRAS-mutated tumour cells." (PMID 34359657, 2021). "Materials and Methods: We detected EGFR and KRAS mutations in paired plasma and tumor tissue samples from 147 NSCLC patients." (PMID 33442424, 2021). "Three samples were found to contain a low frequency of KRAS mutation, which implied low tumor purity." (PMID 34368001, 2021). "This was especially evident in patient 1, where we only found a KRAS mutation in a punch from the primary resection of the tumor, and afterwards a KIT mutation in the extensive resection of the same tumor." (PMID 34072863, 2021). "KRAS G12 mutations were detected in 6 of 8 specimens containing > 20% tumour from independent Sanger sequencing." (PMID 33704908, 2021). "The KRAS gene can simultaneously harbor multiple mutations that can potentiate tumor-promoting activity in several human cancers; thus, it is necessary to utilize a new therapeutic strategy to inhibit this oncoprotein and therefore the development of cancer." (PMID 34744708, 2021). "Regarding the correlation between KRAS mutations and tumor site, there is some dissimilarity in the literature." (PMID 33784337, 2021). "These are diagnosed at early stages, and tumor growth is stepwise and encompasses mutations in KRAS, BRAF, PIK3CA, and PTEN." (PMID 34721577, 2021). "In this study, it was shown that overall median fractional abundance for KRAS mutations in cfDNA was approximately 50-times lower than in tumor DNA (0.23% versus 9.84%)." (PMID 33669856, 2021). "It is reported that ferroptotic cancer cells can drive tumor-associated macrophage polarization through releasing oncogenic KRAS protein." (PMID 34316400, 2021). "A novel molecule selectively targeting ERK, SCH772984, induced tumor regression in mouse xenograft models with KRAS or NRAS mutations." (PMID 34301278, 2021). "Other important factors include CpG island methylator phenotype status, BRAF and KRAS mutational status, tumor differentiation (grade), location (right-sided vs. left-sided), and colon microbiota." (PMID 35008550, 2021). "By retrieving tumor purity scores computed by integrating independent lines of evidence, we found that indeed TCGA samples derived from KRAS-mutated lung tumors had higher purity scores than EGFR-mutated tumors." (PMID 34344431, 2021). "Mutated, oncogenic KRAS-sEVs were characterized by tumor-promoting proteins, including mutant KRAS, and an altered miRNA content, enabling oncogenic transfer and metabolic reprograming in recipient cells." (PMID 34503190, 2021). "Our data indicate a benefit of aspirin usage particularly for patients with combined wild-type PIK3CA and mutated-KRAS tumor characteristics." (PMID 34638442, 2021).
tumor (continued). "KRAS oncogenic driver mutations are responsible for these tumor cells highly relying on OXPHOS for survival (by supplying ATP) as well as drug resistance (via multidrug transporters)." (PMID 34376225, 2021). "For this purpose, we compared pretreatment biopsy samples and plasma circulating tumor DNA (ctDNA) at the time of PD for the KRAS G12C mutation." (PMID 34943432, 2021). "It should be noted that all tumor-bearing animals were heterozygous for the FSF-KrasG12D since this targeted insertion is a functional null allele of KRAS that causes embryonic lethality in a homozygous configuration." (PMID 34675248, 2021). "Alternatively, some genes comutated with a KRAS allele less frequently than expected by chance, suggesting they were functionally redundant mutations or introduced an inhibitory effect on the tumor’s progression." (PMID 33753749, 2021). "Within the group of patients with KRAS mut tumours, G12C was the most frequent mutation in former/current smokers (45%), while G12D was more frequent in KRAS mut never smokers (46%; p = 0.016)." (PMID 34503114, 2021). "Among patients with KRAS mutated tumours, 407 (97%) were current or former smokers and 13 (3%) were never smokers (p < 0.001)." (PMID 34503114, 2021). "The only tumor (T31) in which different mutations were observed between both areas was a MMRp tumor showing a KRAS mutation in the glandular area and PIK3CA mutation in the solid area." (PMID 33435234, 2021). "Here, we compared the frequency and mutation burden of KRAS mutation subtypes with paired tumor tissue and blood in patients and examined their clinical significance." (PMID 34829828, 2021). "Around half of these KRAS-mutated tumours harbour G12C point mutations, which favour the active GTP-bound state of KRAS to drive downstream oncogenic signalling." (PMID 35602221, 2021). "KRAS mutations are often associated with high tumor mutation burdens, elevated PD-L1 expression, and an immunosuppressive tumor microenvironment." (PMID 34073318, 2021). "We combined inhibitors of ACK1 and AKT to suppress the over-activation of downstream signaling caused by KRAS mutation, thereby inhibiting tumor progression." (PMID 32530390, 2021). "Here, we analyze 13,492 samples from these four tumor types to examine allele- and tissue-specific genetic properties associated with oncogenic KRAS mutations." (PMID 33753749, 2021). "Other studies have also suggested that patients whose primary tumour carried a KRAS mutation are more likely to develop lung metastasis during disease progression." (PMID 33802849, 2021). "In multivariate cox regression, over 65-year-old, history of colon polyps, and KRAS mutation were also risk factors; anatomic neoplasm subdivision, BMI < 23.5, pMMR, and new tumor after initial treatment were protective factors." (PMID 34526059, 2021). "Among these, variants in specific codons of the Kirsten RAS (KRAS) oncogene are of particular interest due to their ability to predict tumor response to anti-epidermal growth factor receptor (EGFR)-targeted therapies." (PMID 34640513, 2021). "The mutational status of KRAS gene was compared between FFPE tumour tissues and basal cfDNA samples from the same patient." (PMID 33953347, 2021). "A previous study showed that B7-H3, T-cell immunoglobulin mucin family member 3, and indoleamine 2,3-dioxygenase-1 were highly expressed in tumor stroma-associated inflammatory cells in LUADs harboring KRAS mutations." (PMID 34885068, 2021).
tumor (continued). "In non-small cell lung cancer models driven by the KRAS[Gly12Asp] mutation, the tumour suppressive activity of LKB1 has been reported to be dependent on SIK1 and SIK3." (PMID 33861845, 2021). "The KRAS gene mutations occur in more than 90% of pancreatic cancer (PC), and appears therefore as the best candidate to assess the presence of ctDNA in this tumor." (PMID 34638228, 2021). "Higher SAA expression was detected in tumours that harboured oncogenic KRAS activating mutations compared to control tissue in our study." (PMID 34203378, 2021). "As consequence, these missense mutations cause a constitutive activation of KRAS downstream pathways and promote cell proliferation and tumor development." (PMID 35004317, 2021). "Detected point mutations of the KRAS gene in tumor tissues were monitored in the blood of each patient who underwent chemotherapy." (PMID 34675229, 2021). "PDXs demonstrated response to radiation, response to selumetinib in tumors harboring KRAS G12C mutations and response to savolitinib in a tumor with MET exon 14 skipping mutation." (PMID 33510214, 2021). "Although the present findings provide new insights into the impact of KRAS mutation on the tumor microenvironment of CRC, there are limitations to our work." (PMID 33413474, 2021). "As in the metastatic setting, these data argue against employing Wnt inhibitors for APC-deficient tumours, but advocate their use for BRAF/KRAS-mutated serrated tumours that lack APC mutation (encompassing subsets of CMS1, CMS3, and CMS4 tumours)." (PMID 33673710, 2021). "Antigen specific T-cell generation was observed in most patients with a prolonged stable disease most notably observed in those with KRAS mutated tumours, as well as those treated with immune checkpoint inhibitors following BN-CV301." (PMID 33546207, 2021). "The tumor of patient 2 revealed a high proportion of KRAS p.G12A mutated cells (64.2%), concordant with our previous results and reflecting an amplification of the mutant allele, but no NRAS mutation (tumor cell content of the whole section: 70%)." (PMID 34072863, 2021). "Tumor material was also unavailable in 10 of the controls, with two having detectable variants in KRAS, of which one was a clinically relevant variant (p.Gly12Ala, AF: 0.06%)." (PMID 34217228, 2021). "Somatic mutations of BRAF and KRAS are frequent in some tumour subtypes and are retained in the corresponding organoids even after long-term passaging." (PMID 33580825, 2021). "The resistance of KRAS-mutated tumours to RAF or MEK inhibitors is usually caused by ERK feedback activation." (PMID 34012925, 2021). "Our findings show that KRAS and NRAS mutations especially KRAS mutations have distinct clinicopathological features (tumor site, MSS status, positive lymph node...)." (PMID 33784337, 2021). "We successfully cultured tumour samples from major different pathways of CRC pathogenesis: MSI-high phenotype; MSS with BRAFV600E, possibly representative of a CIMP-positive phenotype; KRAS mutated tumours." (PMID 34572922, 2021). "All patients had genomic sequencing on their tumor or liquid biopsy performed, confirming the KRAS mutation before commencing." (PMID 34901697, 2021). "Another important factor to consider is the high rate of mutation of tumor-promoting proteins such as KRAS and EGFR in signaling pathways causing acquired resistance to targeted therapy." (PMID 34162394, 2021).
tumor (continued). "Non-small-cell lung cancer (NSCLC) with Kirsten RAt Sarcoma 2 viral oncogene homolog (KRAS) mutation has become a clinical challenge in cancer treatment as KRAS-mutant tumors are often resistant to conventional anti-tumor therapies." (PMID 32530390, 2021). "The mean survival time was shorter among patients with KRAS mutations than among patients with wild type KRAS tumours (54.46 vs. 58.02 months)." (PMID 33979337, 2021). "In support of the existence and relevance of RAS dimers in vivo, the expression of an oncogenic KRAS dimerization mutant in transgenic mice resulted in the loss of the tumor suppressor effect of wildtype KRAS, which is thought to be exerted by dimerization." (PMID 33562401, 2021). "A close relationship between the KRAS mutation and the amount of cancer stroma (tumor stromal percentage, TSP) has also been suggested." (PMID 34272423, 2021). "Our data indicated a benefit of aspirin usage particularly for patients with combined wild-type PIK3CA and mutated-KRAS tumor characteristics." (PMID 34638442, 2021). "The patients were treated with the standard-of-care combination palbociclib plus fulvestrant as first-line metastatic therapy, and before starting treatment, they were assessable for the analysis of KRAS mutations in tumour tissue and in their ctDNA." (PMID 33923563, 2021). "We evaluated the capacity of TST170 to detect gene variants in cfDNA from a retrospective cohort of 20 metastatic CRC patients with known KRAS variants in tumor tissue and in cfDNA previously analyzed by pyrosequencing and BEAMing, respectively." (PMID 34640513, 2021). "KRAS signaling is oncogenic and was reported to regulate tumor-associated immune responses such as inducing cancer cell evasion from immunosurveillance." (PMID 33708243, 2021). "The authors determined that KRAS knockout (KO) PDA cells had a striking up-regulation of major histocompatibility complex I (MHC I) genes compared with KRAS intact control cells, underlying increased susceptibility to anti-tumor immunity." (PMID 34290984, 2021). "The molecular hallmark of PDAC is KRAS mutation, a near ubiquitous and critical oncogenic driver of tumor initiation and progression." (PMID 33996827, 2021). "Epigenetic, metabolic, and immuno-modulatory processes have all been implicated in drug resistance and tumor maintenance in KRAS-mutant PDACs." (PMID 33796221, 2021). "An additional limitation was the absence of detailed clinicopathological data regarding disease history, other co-morbidities and tumor characteristics (including its KRAS mutational status)." (PMID 34629961, 2021). "Instead, mutant KRAS with up-regulation of the nuclear factor erythroid 2-related factor 2 (NRF2) causes rearrangement of glutamine metabolic pathways in tumor cells." (PMID 34604242, 2021). "In our series, for example KRAS was found mutated at the well-known hotspot exon 2 codon 12/13 site in 7 of the 48 tumor samples." (PMID 33500480, 2021). "The destabilization of Ras via RTKs can be a promising strategy to halt a tumor in KRAS-mutated NSCLC." (PMID 34769090, 2021). "In some patients, the analysis of KRAS variants in cfDNA with TST170 showed some discordance with respect to the cfDNA analyzed by BEAMing or the status of tumor tissues." (PMID 34640513, 2021). "As PDAC exhibits the highest frequency of KRAS mutations, KRAS is likely to be the best-characterized tumor-related gene that also occurs at an early stage of PDAC." (PMID 35582309, 2021). "KRAS mutations have been associated with tumour-promoting inflammation and play a key role in carcinogenesis by inducing an array of inflammatory cytokines, chemokines and signalling pathways that promote tumorigenesis and invasiveness." (PMID 34064232, 2021).
tumor (continued). "Despite the sequential acquisition of additional genomic alterations that contribute to mold the course of PDAC development, KRAS mutations strongly influence tumor maintenance and metastasis." (PMID 34957115, 2021). "Some instances of differential mutational signature composition between tumor samples with different KRAS alleles were identified, though they tended to be differences in magnitude of the signatures, not their presence or absence." (PMID 33753749, 2021). "Here, we demonstrate a cell-extrinsic role of KRAS, where KRAS engages with the tumor microenvironment by functional reprogramming of tumor-associated macrophages (TAMs)." (PMID 33833221, 2021). "It is necessary to verify these results in larger cohorts and elucidate the mechanism how the KRAS mutation affects the infiltration of various immune cells in the tumor microenvironment." (PMID 34272423, 2021). "In the report, interleukin-33 (IL-33) was further identified as the effector that dominates environmental damage-induced early neoplasia and neoplastic transformation in the presence of KRAS mutation." (PMID 34023857, 2021). "In LUAD cohort, the mutation ratio of KRAS, an oncogene which leads to immune escape in the tumor microenvironment, and PTPRD, which affects the tumor proliferation, were higher than LUSC also suggests the difference immune response mechanisms." (PMID 33927719, 2021). "The inactivating mutations in KEAP1 and LKB1, as well as the activation of the YAP1 and/or RSK-mTOR pathway, contribute to mutant KRAS independency in tumor cells, potentially causing therapeutic resistance to KRAS inhibitors." (PMID 34885068, 2021). "Although mutations in KRAS are the most common pan-cancer, certain tumour types show other isoform predilection." (PMID 34200676, 2021). "Of 20 patients with isolated CRC‐PM, 11 (55%) had a KRAS or BRAF tumor tissue mutation and were selected for cfDNA analysis." (PMID 33635598, 2021). "The KRAS mutation is associated more strongly with a history of heavy smoking and higher tumor mutation burden”." (PMID 34575691, 2021). "Analogous analyses in the validation dataset showed that tumor stage (P < 0.001), KRAS mutation (P = 0.048), and risk score (P < 0.001) were closely connected with patient survival." (PMID 34898475, 2021). "The presence of KRAS mutant ctDNA was shown to be strongly correlated with tumour grade and was independently associated with a poorer overall survival in patients." (PMID 33451936, 2021). "Because p-eIF2α impacts on gene transcription, we performed RNA-seq of KRAS G12D eIF2αS/S and eIF2αA/A tumor cells to identify genes and pathways potentially linked to observed differences in tumor phenotypes." (PMID 34330898, 2021). "Recently, it was recognized that mutant KRAS regulates tumor-associated immune responses and induces the protumorigenic properties of immune cells." (PMID 34272423, 2021). "To investigate tumor‐derived cfDNA using sensitive and validated PCR‐based assays, we focused on the detection of KRAS and BRAF mutations." (PMID 33635598, 2021). "The incidence of KRAS mutation was higher in poorly differentiated tumours (33.4% vs. 17.6%) (P=0.02)." (PMID 34557315, 2021). "The anti-EGFR/VEGFR2 BsAb described here demonstrates anti-tumor activity in TNBC cells including MDA-MB-231 cells which harbor KRAS mutation." (PMID 33804477, 2021). "Another approach to examine the impact of mutagenic processes on allele specificity was to compare the probability of obtaining a certain KRAS mutation between tumor samples with the specific mutation, a different KRAS mutation, or WT KRAS." (PMID 33753749, 2021).